HMGB3 (high mobility group box 3)
Diseases named in the same sentence as HMGB3 in open-access papers (continued):
Sharing a sentence is not in itself a finding about the gene and the disease.
tumor (continued). "High mobility group protein B3 (HMGB3) is abundantly expressed in a number of malignancies, contributing to tumor cell growth and predicting poor outcomes." (PMID 36620553, 2022). "The results showed that the expression of ACACB, ATP8B4, C14orf28, CIRBP, and DTWD1 were higher in normal tissues, and the content of CDC6, DSP, HMGB3, HNRNPA3P1, PPP1R14C, and TPX2 were higher in tumor tissues." (PMID 35778922, 2022). "The CEACAM5, HMGB3, and ASS1 genes were specifically expressed in tumor cells from the tumor sample groups (tLung, tL/B, mLN, and mBrain)." (PMID 36397035, 2022). "HMGB3 is considered to be an oncogene and a hub gene in tumor growth, participating in the growth, migration, invasion, immune escape, and even EMT of tumor cells." (PMID 35754798, 2022). "To apply the prescreening process as a single-tube reaction, we performed multiplex RT-PCR analyses using CEACAM5, HMGB3, and ACTB probes with different fluorescence dye formats, which resulted in consistent tumor-specific detection." (PMID 36397035, 2022). "The authors identified a proteomic signature based on 3 proteins (DHB12, HMGB3, and COBA1) and developed a model that included the 3 proteins and tumor stage that exhibited >80% predictive accuracy for the development of metastasis and recurrence." (PMID 35756403, 2022). "Consistent with cell experiments, miR-374b-5p expression was upregulated in EOC tumor tissues by GLA treatment, whereas the levels of HMGB3, Wnt3a, and β-catenin were downregulated (P < 0.05)." (PMID 35912216, 2022). "The tumor volumes in the PLKO.1 group were significantly higher than those in the shHMGB3 group, demonstrating the chemoresistant role of HMGB3 in vivo." (PMID 35332131, 2022). "In tumour xenograft angiogenesis models and clinical samples, HMGB3 was closely correlated with the microvessel density (MVD), indicating that changes in HMGB3 levels in tumour cells regulate angiogenesis." (PMID 34050127, 2021). "EZH2, HMGB3 and UCK2 expressed higher in tumor compared with normal tissues, while NOTCH2 and ODF2 expressed lower in tumor compared with normal tissues." (PMID 32699528, 2020). "In vertebrates, the interaction between HMGB3 and TLR3, TLR7, and TLR9, which occurs on the membrane, leads to upregulation of the production of ROS and activation of NF-kB signaling, which ultimately regulates tumor growth and metastasis." (PMID 39062899, 2024). "In the TCGA-UCEC dataset, APOBEC3G, CUL4B, SCML2, TSPYL5, and ZBTB16 were significantly downregulated in tumor samples, whereas FOXP3, HJURP, HMGB3, and RAC3 were significantly upregulated in tumor samples, which was generally consistent with the result observed in GSE17025." (PMID 36936912, 2023). "Further, we employed SCENIC to predict transcription patterns of tumor cells, finding a series of key TFs of HCC tumorigenesis, such as TFs in regulation of cell dedifferentiation (SPI1, HMGB3, and YBX1) and in abnormal bile acid metabolism (NR1H4, NR1I3, FOXA3 and DDIT3)." (PMID 37985711, 2023). "Furthermore, nEXO HMGB3, secreted by NPC cells, promoted tumour metastasis by inducing angiogenesis." (PMID 34050127, 2021). "The findings of the present study indicate nEXO HMGB3 as a biomarker of NPC metastasis and therefore, may advance the development of novel anti-angiogenesis therapy for tumour metastasis." (PMID 34050127, 2021). "LncRNA SNHG5 serves as a tumor promoter in NPC by sponging miR-1179 and upregulating HMGB3." (PMID 32131767, 2020). "By analyzing normal liver tissue (n = 50) and HCC cases (n = 371) released by TCGA database, we found that HMGB3 expression was higher in the tumor group compared to the normal group (P = .018)." (PMID 30343649, 2018). "For example, TFs, such as ASH1L, CFLAR, HMGB3, ZNF160 and MATR3, displayed opposite behaviors on some cytokines; inflammatory factors; nuclear and tumor factors, such as IL-2, IL-6, NF-κB, and Irf3; immunogenic nucleic acids; papillomavirus E7/E6; caspase-3/caspase-8; Toll-like receptor; and so on." (PMID 28719625, 2017).
tumor (continued). "However, the specific mechanisms of HMGB3 in CRC tumor development have not been effectively explored." (PMID 35712661, 2022). "Therefore, we confirmed that nEXO HMGB3 could be a significant biomarker of NPC metastasis, thereby providing novel insights into the clinical application of anti-angiogenesis therapy for tumours." (PMID 34050127, 2021). "Compared with the MRI data before and after radiotherapy, the tumor volume of the patients with high expression of HMGB3 and hTERT did not significantly change, and the tumor volume of the patients with low expression of HMGB3 and hTERT decreased significantly or even disappeared." (PMID 33187536, 2020). "In addition, it was shown that HMGB3 protein could bind to chemotherapeutic drug–induced damage DNA, leading to the activation of ATM‐and Rad3‐related protein, thus promoting the drug resistance of tumor cells." (PMID 35754798, 2022). "CEACAM5 and HMGB3 showed significant differences in expression between the two groups, and PLAU and ASS1 showed slightly higher expression in tumor tissues, but the difference was not statistically significant." (PMID 36397035, 2022).
cancer (46 papers, 2015 to 2025). A tumor composed of atypical neoplastic, often pleomorphic cells that invade other tissues. "According to the analysis of the TCGA database, another group of genes (SPARC, MKI67, CENPF, CDK1, RHOU, and POLR2D), which includes the HMGB3 gene, is associated with a poor prognosis in cancer." (PMID 39062899, 2024). "HMGB3 is a crucial mediator of cancer development and associated with chemoresistance during cancer progression." (PMID 36276139, 2022). "Conversely, HMGB3 overexpression activates MAPK/ERK signaling to promote cancer stemness and chemoresistance, suggesting a dosage-dependent role in senescence escape." (PMID 40299498, 2025). "HMGB3 depletion can sensitize cancer cells to several DNA-damaging drugs, and given the physical similarities to HMGB1, it is feasible that these two proteins have somewhat redundant functions." (PMID 41009989, 2025). "High mobility group box 3 (HMGB3) is highly expressed in stem cells and cancer cells and is rarely activated in normal adult tissue." (PMID 37588193, 2024). "HMGB3 is expressed at high rates in stem cells and cancer cells and is rarely upregulated in normal adult tissues, making it a promising therapeutic target." (PMID 39062899, 2024). "Specifically, we have identified that ELAVL1 enhances HMGB3 mRNA stability and regulates the Wnt/β-catenin signaling pathway, thereby promoting glycolysis in cancer cells." (PMID 39390359, 2024). "circRUNX1 promotes cancer cell progression by enhancing proliferation and metastasis through regulation of the miR-5195-3p/HMGB3 axis." (PMID 39062899, 2024). "In somatic cells, HMGB3 is expressed at a very low level; in stem and cancer cells, it is significantly upregulated." (PMID 39062899, 2024). "During the development and progression of cancer cells, HMGB3 expression is regulated by miR-206, miR-205, miR-27b, and miR-205-5p." (PMID 39062899, 2024). "HMGB3 has been demonstrated to regulate several carcinogenic signaling pathways in multiple types of cancer." (PMID 37328851, 2023). "HMGB3, from the high-mobility group box subfamily, participates in the cell proliferation, metastasis, and apoptosis in cancers." (PMID 35912216, 2022). "By the Ualcan website, we analyzed the expression of HMGB3 in cancer and normal tissues and found that HMGB3 was highly expressed in most of the tumors (20/24)." (PMID 35712661, 2022). "We also analyzed the correlation between HMGB3 expression levels and cancer prognosis in the GEPIA database." (PMID 36620553, 2022). "Among the 11 coding genes, HMGB3 was widely reported to promote malignant progress and predict poor survival in various cancer types." (PMID 35778922, 2022). "High-mobility group box 3 (HMGB3) plays significant roles in the development of drug resistance of many cancers." (PMID 35332131, 2022). "HMGB3 is highly expressed in stem cells and cancer cells and is rarely transactivated in normal adult tissues, making it a promising therapeutic target." (PMID 35332131, 2022). "HMGB proteins are closely related to DNA damage repair, among which HMGB3 is often overexpressed up to 20 times in cancer cells." (PMID 36003381, 2022). "Within the HMGB family, HMGB3 expression was associated with MSI and (or) TMB in most cancer types, consistent with its highest alternation occurrence rate in pan-cancer." (PMID 34777483, 2021). "The effects of HMGB3 on NB not only provide new insight into the survival mechanism of cancer cells but also reveal a potential implication of HMGB3 in prognosis and a novel therapeutic strategy for NB." (PMID 34988076, 2021). "Despite that the overexpression of HMGB1 in cancers was the most prevalently reported, we found that HMGB3 was highly expressed in the largest variety of cancers and altered most frequently." (PMID 34777483, 2021). "High mobility group box 3 (HMGB3) plays an oncogenic role in many cancers; however, its biological role in NB is still unclear." (PMID 34988076, 2021).
cancer (continued). "HMGB3 is a DNA-binding protein that helps maintain stem cell populations and is overexpressed in some human cancers via the Wnt signaling pathway." (PMID 34579650, 2021). "HMGB3 is a well-known oncogenic member of chromatin-binding proteins that can regulate gene expression in various cancers via transcription factor binding modulation." (PMID 33652661, 2021). "Studies have indicated that HMGB3 promotes cancer cell proliferation by activating the WNT/β-catenin pathway." (PMID 34988076, 2021). "Compared with the cancer clusters, HMGB3, EZH2 and ZNF76were identified as candidate transcription factors whose expressions were specifically regulated in the CSC cluster." (PMID 33162821, 2020). "Therefore, understanding the role(s) of HMGB3 in cells can shed further light on the mechanisms behind these observations and provide information on HMGB3 as a potential target in cancer treatment." (PMID 41009989, 2025). "Consequently, we selected HMGB3 as the specific marker for identifying the cancer stem like-B cell subpopulation and validated it by immunofluorescence staining." (PMID 38149239, 2023). "HMGB3 is proven to mediate cancer cell stemness in many malignancies." (PMID 37328851, 2023). "Notably, HMGB3 is highly expressed and plays a vital role in the malignant progression of a variety of cancers." (PMID 35332131, 2022). "HMGB3 participates in modulating cancer development by affecting the Wnt-β-catenin pathway." (PMID 35912216, 2022). "HMGB3 also promotes self-renewal and colony formation of cancer stem cells and cancer cells." (PMID 35754798, 2022). "HMGB3 is involved in the recurrence, progression, and drug resistance of various cancers." (PMID 35912216, 2022). "Therefore, up-regulation of HMGB3 eliminated the inhibition of miR-216a demethylation on HMGB3 and promoted cancer cell proliferation, invasion, and migration." (PMID 33842327, 2021). "Notably, HMGB3 has been an attractive target for a wide variety of cancers, but HMGB3-targeted studies for NPC and exosomes containing HMGB3 have not been reported." (PMID 34050127, 2021). "We also examined HMGB3 mRNA level in CRC samples in relative to non-carcinoma samples." (PMID 34753396, 2021). "The dysregulation of HMGB3 has been identified in many human cancers." (PMID 32131767, 2020). "Additionally, it has been reported that inhibition of HMGB3 induced by miR-205-5p inhibited cancer cell aggressiveness and was involved in prostate cancer pathogenesis." (PMID 32131767, 2020). "High mobility group box 3 (HMGB3) is an identified oncogene in the development of human cancers." (PMID 32871048, 2020). "Thus, in vivo and in vitro, inhibition of HMGB3 has been shown to impair cancer cell proliferation." (PMID 39062899, 2024). "However, the particular functions of HMGB3 in the development of resistance to chemo- and radiotherapies in various types of cancer remain unclear." (PMID 39062899, 2024). "Moreover, the dysregulation of HMGB3 has been found in many human cancers." (PMID 32131767, 2020). "What is more, genes positively correlated with HMGB3 in BRAC were also enriched in pathways of amino acids and carbon metabolism, indicating their participation in cancer metabolic alternations." (PMID 34777483, 2021). "Integrating the results of two steps of survival analyses, high expression of HMGBs suggested unfavorable prognosis in the following cancers: HMGB1 in ACC; HMGB2 in ACC, KIRP, LGG, LIHC, MESO; and HMGB3 in BRCA, ESCA, SARC, and SKCM." (PMID 34777483, 2021). "Furthermore, we identified key transcription factor regulatory networks regulated by HMGB3, SAP30, and E2F8, which likely played crucial roles in the functional characterization of the cancer stem cell-like B cell subpopulation." (PMID 38149239, 2023). "Unlike HMGB1 and HMGB2, HMGB3 is expressed at low levels in normal cells but often overexpressed (up to 20-fold) in cancer cells." (PMID 34050127, 2021).
cancer (continued). "In addition, elevated HMGB expression indicated clinicopathological advances in these cancers: HMGB1 in ACC, HNSC, and ESCA; HMGB2 in ACC, HNSC, KIRC, LGG, and LIHC; and HMGB3 in ESCA and HNSC." (PMID 34777483, 2021). "High mobility group box 3 (HMGB3), a nuclear protein, is known to be overexpressed in cancers." (PMID 34050127, 2021). "Integrating the significance of prognosis, TIICs, ICP genes, and MSI and (or) TMB, we induced that HMGBs might be promising immunological targets for the following cancers: HMGB1 for ACC and KIRC; HMGB2 for ACC and LGG; and HMGB3 for BRAC, SARC, SKCM, and OV." (PMID 34777483, 2021). "Future investigation on how HMGB3 is involved in ICL and DSB repair, and subsequently, drug resistance in cancer cells, may allow for the development of improved therapies for cancer treatment and to improve the quality of life of cancer patients." (PMID 41009989, 2025). "Additionally, we identified the key transcription factor regulatory networks regulated by HMGB3, SAP30, and E2F8 that may play important roles in the functional characterization of the cancer stem cell-like B cell subgroup." (PMID 38149239, 2023). "HMGB3 may be more suitable as a target for cancer treatment because of the high expression and non-proinflammatory effect." (PMID 33187536, 2020).
infection (6 papers, 2016 to 2024). The state of being infected such as from the introduction of a foreign agent such as serum, vaccine, antigenic substance or organism. "Indeed, we observed that infection by necrotrophic B. cinerea caused release of HMGB3 into the apoplast within 24 hours after inoculation." (PMID 27007252, 2016). "On the other hand, knockdown of HMGB3 (High Mobility Group Box 3) resulted in an increase in Tat transactivation and translation as well as an increase in productive infection." (PMID 34194479, 2021). "In this study, we showed that i) infection by a necrotrophic pathogen releases plant HMGB3 into the apoplast, ii) extracellular, HMGB3 activates immune responses, iii) SA binds to HMGB3, and iv) this binding alters its DAMP activity." (PMID 27007252, 2016). "In this scenario, release of HMGB3 to the extracellular space would occur when cells are damaged during infection by necrotrophic pathogens." (PMID 27007252, 2016). "Interestingly, these effects correlated with the levels of the proteins in rCD4+ T cells following HIV‐1 infection as we observed a decrease in SRp14 levels while HMGB3 peaked very quickly after infection in rCD4+." (PMID 30051631, 2018). "Infection by necrotrophic B. cinerea released HMGB3 into the extracellular space (apoplast)." (PMID 27007252, 2016). "An increase in productive infection was detected after knockdown of FLNA, HMGB3, PTBP1, HSP90AA1, and KIF2C (green bars)." (PMID 34194479, 2021). "The ISD bait method was validated by identifying known dsDNA sensors including HMGB1, HMGB2, and HMGB3, components of the AIM2 inflammasome, and the SET complex that plays a role in HIV-1 retroviral detection and infection." (PMID 33042865, 2020). "High-mobility group box 3 (HMGB3; also known as HMG2A or HMG4) is a member of the high-mobility group protein family, which plays vital roles in DNA recombination, repair, and replication, and whose members act as cytokines to mediate responses to infection, injury, and inflammation." (PMID 37328851, 2023). "Interestingly, two genes, SRP14 and HMGB3 have not been previously reported to play a role in the regulation of HIV-1 replication and their knockdown here had very marked effects on latent and productive infection, respectively." (PMID 34194479, 2021).
genetic disorders (1 paper, 2022). "We explored whether there is a correlation between genetic disorders and HMGB3." (PMID 35712661, 2022).
HMGB3 also shares sentences with these, for which no sentence is quoted: ovarian serous cystadenocarcinoma (2 papers); bladder urothelial carcinoma (1); breast invasive carcinoma (1); diffuse large B-cell lymphoma (1); endometrial cancer (1); gastrointestinal tumors (1); inflammation (1); lipoma (1); melanoma (1); mesenchymal tumors (1); myocardial infarction (1); pancreatic ductal adenocarcinoma (1); pulmonary hypertension (1); skin cutaneous melanoma (1); testicular germ cell tumor (1); ulcerative colitis (1); uterine corpus endometrial carcinoma (1); viral infection (1).